VGLL4 (vestigial like family member 4)
Diseases named in the same sentence as VGLL4 in open-access papers (continued):
Sharing a sentence is not in itself a finding about the gene and the disease.
tumor (continued). "Our current study revealed VGLL4 as a tumour suppressor in CRC and highlighted its potential anti-cancer application as a targeted therapy aiming at both Wnt/β-catenin and Hippo-YAP signalling." (PMID 28051067, 2017). "They reported that GC tumor growth can be suppressed in vitro and in vivo by the peptide mimicking function of VGLL4." (PMID 29069755, 2017). "Taken together, these observations support the proposal that VGLL4 functions as a CRC tumour suppressor at least partially through downregulation of Wnt/β-catenin signalling." (PMID 28051067, 2017). "We next evaluated the role of VGLL4 in tumour formation of HCT116 and SW480 cells by using a xenograft model of nude mice." (PMID 28051067, 2017). "Both tumor growth rate and tumor size were dramatically reduced for VGLL4-overexpressing cells compared with control cells." (PMID 28733631, 2017). "VGLL4 was downregulated in CRC, with its expression level being inversely correlated with those of Wnt/β-catenin and Hippo-YAP target genes, indicating that VGLL4 acts as a tumour suppressor in CRC by co-regulating both signalling pathways." (PMID 28051067, 2017). "The Tondu domains of vestigial-like family member 4 (VGLL4) interact directly with YAP, thereby preventing YAP-TEAD interactions, and a VGLL4-mimicking peptide disrupting YAP-TEAD interaction suppressed tumour growth in mice." (PMID 25097725, 2014). "Therefore, due to its role as a tumor suppressor, VGLL4 has the potential to serve as a targeted therapy for various types of cancer." (PMID 38255254, 2024). "Notably, vestigial like family member 4 (VGLL4) was identified as a tumor suppressor that competes with YAP for binding to TEA domain transcription factors (TEADs), thus inhibiting YAP and TAZ transcriptional activity." (PMID 37799806, 2023). "LINC00641 is a tumor suppressor lncRNA in PCa, and modulates miR-365a-3p/VGLL4 axis." (PMID 37025585, 2023). "The genes validated as targets of miR-365b included EPN1, H2AFY, PI3KR3 and VGLL4, in which all have been reported as players in tumor biology, and interestingly both VGLL4 and EPN1 were shown to be involved in regulation of Wnt-signaling, a pathway that is dysregulated in MM40." (PMID 35840794, 2022). "Terminal deoxynucleotidyl transferase dUTP Nick-End Labeling (TUNEL) studies of HCC tumor tissue sections confirmed that Ad-sp-VGLL4 promoted apoptosis in HCC in vivo, and HE-staining demonstrated that Ad-sp-VGLL4 inhibited angiogenesis and caused damage in HCC." (PMID 36146619, 2022). "Several Hippo pathway tumor suppressors, including Lats2, Mst1, and Mst2, were also slightly increased in Vgll4 mutant livers, consistent with the well-established negative feedback whereby activation of the nuclear effector YAP leads to up-regulation of upstream tumor suppressors." (PMID 36522128, 2022). "Thus, VGLL4 appears to be a PD-L1 expression regulator and plays a key role in the VGLL4 and YAP association in tumor immunity modulation." (PMID 33996817, 2021). "Vestigial Like Family Member 4 has been described as a tumor suppressor in many cancers." (PMID 34150758, 2021). "What are the molecular mechanisms of VGLL4 down-regulation in tumor cells?" (PMID 32793503, 2020). "MicroRNA-independent mechanisms of VGLL4 repression in tumor have also been reported." (PMID 32793503, 2020). "VGLL4, a new member of the Hippo pathway, is intensively investigated in inhibition of tumor progression via competing with YAP to bind TEADs, but its role in cardiovascular field remains unclear." (PMID 30789911, 2019). "In addition to VGLL4, the other IAP-binding protein, X-linked inhibitor of apoptosis (XIAP)-associated factor 1 (XAF-1), is also regarded as a tumor suppressor." (PMID 31781493, 2019). "VGLL4 overexpression acts as a tumor suppressor in TNBC cells both in vitro and in vivo." (PMID 31748508, 2019). "As expected, Ad-sp-VGLL4 possesses a strong anti-tumor capacity." (PMID 31781493, 2019).
tumor (continued). "More importantly, VGLL4 significantly inhibits tumor progression in a nude mouse model." (PMID 31748508, 2019). "Our findings indicated that miR‐301b‐3p might be considered as a potential prognostic marker and contributed to tumour growth of human HCC by targeting vestigial like family member 4 (VGLL4)." (PMID 31207037, 2019). "Furthermore, in animal experiments, overexpression of VGLL4 inhibited the growth of TNBC cells in vivo, and the tumor volume and weight in the VGLL4 overexpression group was decreased significantly compared with those in the NC group." (PMID 31748508, 2019). "VGLL4 acts as a tumor suppressor by interfering with a signaling pathway that drives tumor growth." (PMID 31748508, 2019). "Additionally, ALP, GGT, tumor size, 5-HT level and YAP/VGLL4 ratio were all associated with overall survival and recurrence-free survival via univariate analysis." (PMID 29950605, 2018). "Knockdown of VGLL4 enhances proliferation and tumour formation of CRC cells." (PMID 28051067, 2017). "This difference in the N-termini of the two VGLL4 isoforms may lead to changes in protein stability, localization and interaction with other cofactors with possible consequences on VGLL4 tumor suppressor function." (PMID 28642487, 2017). "Notably, our study indicates that the tumor-inhibiting functions of VGLL4 are mediated via its TDU2 domain." (PMID 28733631, 2017). "However, in this context one should note that the anti-tumour activity of compounds, such as VP or VGLL4 peptides, is yet to be examined in the setting of established tumours." (PMID 25097725, 2014). "Similarly, as involvement of RIP5 kinases in either pro-tumor or anti-tumor effect is largely unknown, VGLL4 has been identified as a tumor suppressor gene." (PMID 38255254, 2024). "The increased expression of Hippo pathway tumor suppressors in Vgll4 mutant livers suggests that these mechanisms are functionally coupled and may explain the relative subtle mutant phenotype in Vgll4 mutant livers." (PMID 36522128, 2022). "Our findings reinforce VGLL4’s importance in CRC progression and indicate a need for further investigation into its mechanistic role as a tumor suppressor, especially in CRC cancers." (PMID 39857952, 2025). "Gene expression of AIFM3 (p < 0.0001), VGLL4 (p < 0.0001), and WNT4 (p < 0.01) was significantly altered in tumor tissues in comparison to the control tissues." (PMID 39857952, 2025). "Their representative genes include the tumor suppressor genes LHPP, VGLL4, USP53, and CLDN6, which have been reported to play significant anti-tumor functions in a variety of cancer types." (PMID 38831454, 2024). "Among annotations of differentially enriched regions, we discovered that tumor suppressor genes such as LHPP, VGLL4, USP53, and CLDN6 had increased H3K9ac signals in their promoter regions under the metformin condition." (PMID 38831454, 2024). "Initially identified as a YAP repressor, vestigial-like family member 4 (VGLL4) competes with TEADs for YAP binding, thereby sequestering YAP and exerting tumor-suppressing functions." (PMID 38067201, 2023). "A comparison of the tumor volume growth curves of the PBS and Ad-sp groups revealed that Ad-sp-VGLL4 inhibits the growth of tumors." (PMID 36146619, 2022). "Vestigial-like family member 4 (VGLL4) competes with YAP in binding to TEA domain family members (TEADs) and thus inhibits tumor growth in LUAD." (PMID 34765600, 2021). "Ubiquitin-specific protease 11 (USP11) deubiquitinated and stabilized VGLL4 proteins, and the inactivation of USP11 was suggested to be involved in the destabilization of VGLL4 in tumor cells." (PMID 32793503, 2020). "Although the tumor-suppressing roles of VGLL4 mostly depend on competition with YAP for TEAD binding, VGLL4 also acts as a tumor suppressor in a YAP-independent manner." (PMID 32793503, 2020).
tumor (continued). "USP11 deubiquitinates and stabilizes the vestigial-like family member 4 (VGLL4) protein, which directly competes with YAP by forming a complex with the TEA domain proteins (TEADs), thereby acting as a tumor suppressor." (PMID 33158118, 2020). "Therefore, the transfer of VGLL4 into tumor cells may be an effective therapeutic method." (PMID 32793503, 2020). "Consistent with this repressive effect of VGLL4 on TEAD activity, VGLL4 is recognized as a tumor suppressor gene." (PMID 32793503, 2020). "GPNMB and CoL5A1 are the reported oncogenes; PMEPA1, POMT2, VGLL4 and SUMF1 show better survival and thus suggest tumor suppressive role are being regulated by EZH2 signifying its dual role." (PMID 30760814, 2019). "In this study, the results demonstrated that VGLL4 is expressed at low levels in both TNBC specimens and cell lines and that VGLL4 expression is negatively correlated with Ki67 expression and tumor size in TNBC patients." (PMID 31748508, 2019). "Next, we calculated the YAP/VGLL4 ratio of each patient and found that the average value of YAP/VGLL4 ratios among all HCC patients were much higher compared with non-tumor patients." (PMID 29950605, 2018). "Stable lentiviral depletion of VGLL4 in HCT116 and SW480 cells significantly promoted tumour growth in vivo when compared with the control (scramble)." (PMID 28051067, 2017). "To further evaluate the anti-tumour effect of VGLL4 in CRC, we made use of a peptide that mimics the function of VGLL4 (termed as Super-TDU), which we developed previously for the study of Hippo-YAP signalling." (PMID 28051067, 2017). "Further researches identified VGLL4 could compete with YAP for TEAD binding, which blocked Hippo target gene expression and tumor growth." (PMID 38605077, 2024). "Therefore, a VGLL4-mimicking peptide called “super-TDU” has been designed and showed anti-tumour efficiency in vitro and in vivo." (PMID 36759723, 2023). "Interestingly, Vestigial-like 4 (VGLL4) is an antagonist of YAP/TEAD activity, which can effectively inhibit YAP-driven TEAD expression and suppress PCa tumor growth when overexpressed." (PMID 36359354, 2022). "In addition to verteporfin, a peptide mimicking VGLL4 has also been shown to inhibit YAP-TEAD interaction and suppress tumor growth in vitro and in vivo." (PMID 32596154, 2020). "VGLL4 competitively inhibits binding of YAP and TEAD, thereby acting as a tumor suppressor." (PMID 32540914, 2020). "Further investigation revealed that the downregulation of VGLL4 upregulated the expression of apoptosis-related Bcl-2 and the cell-cycle regulators Cyclin D1, Cyclin E1, and CDK8, and the upregulation of these molecules was conducive to tumor proliferation." (PMID 31748508, 2019). "Additionally, the nomogram based on tumor size, 5-HT and YAP/VGLL4 balance were established in our study." (PMID 29950605, 2018). "Mechanistically, we found that VGLL4 interacts with TEAD1 via its second TEAD-interacting domain (TDU2), selectively antagonizing the TEAD1-YAP1 transcriptional complex and, therefore, YAP-dependent tumor growth." (PMID 28733631, 2017). "Additionally, peptide-based drugs designed on the basis of the α-helical structure of VGLL4, which mimic its competitive binding to TEAD, have shown potential in blocking YAP/TAZ-driven transcriptional activation and reducing tumor cell proliferation and migration." (PMID 40486910, 2025). "Taken together, these results indicate that VGLL4 and RFXANK can directly induce TEAD4 LLPS both in vitro and in vivo, and these condensates may function as repressors of transcription to eventually induce tumor cell apoptosis." (PMID 39358623, 2024). "This evidence indicated that overexpression of VGLL4 in cancer cells might exhibit an anti-tumor effect, not only through YAP-dependent gene induction but also by the apoptosis pathway." (PMID 31781493, 2019).
cancer (22 papers, 2017 to 2026). A tumor composed of atypical neoplastic, often pleomorphic cells that invade other tissues. "Although VGLL4 is rarely mutated in human cancer, it is located at the short arm (3p) of chromosome 3, which is lost in many types of cancer." (PMID 34150758, 2021). "Vestigial Like Family Member 4 can inhibit organ overgrowth and cancer formation caused by YAP1 dysregulation in both human and Drosophila." (PMID 34150758, 2021). "Furthermore, aberrant expression of VGLL4 frequently occurs in various cancers, and its association with cell proliferation, migration, invasion, and epithelial-mesenchymal transition is well-established." (PMID 38544827, 2024). "An increase in the YAP/VGLL4 ratio is associated with cancer progression." (PMID 33859748, 2021). "VGLL4 increases in the affected tissues as the cancer progresses, particularly noticeable from early to more advanced stages." (PMID 39857952, 2025). "VGLL4 suppresses the cancerous phenotype of malignant epidermal squamous cell carcinoma by inhibiting YAP1/TEAD-dependent pro-cancer signaling." (PMID 38831454, 2024). "Strikingly, we also demonstrated that the driving of TEAD4 into the condensate state by VGLL4/RFXANK or an engineered peptide significantly limited cancer cell growth and increased apoptosis." (PMID 39358623, 2024). "The expression level of VGLL4 is lower in many types of cancer compared to normal tissues, and lower expression of VGLL4 usually indicates poor survival in many cancers." (PMID 38255254, 2024). "Together, these findings highlight the central importance of VGLL4-mediated transcriptional repression in Hippo pathway regulation and inform potential strategies to modulate Hippo signaling in cancer and regenerative medicine." (PMID 36522128, 2022). "Their findings highlight the central importance of VGLL4-mediated transcriptional repression in Hippo pathway regulation and inform potential strategies to modulate Hippo signaling in cancer and regenerative medicine." (PMID 36522128, 2022). "A considerable number of works in literature have evidenced that the expression of VGLL4 is significantly weaker compared to healthy tissues in many kinds of cancers." (PMID 34831362, 2021). "In the present study, we validated six direct targets of EZH2 that are GPNMB, PMEPA1, CoL5A1, VGLL4, POMT2 and SUMF1 associated with cancer related pathways." (PMID 30760814, 2019). "5-HT is proved to upregulate YAP expression by our previous study and VGLL4 is found to compete with YAP for binding to TEAD in several of cancers." (PMID 29950605, 2018). "Another implication of our current study is that VGLL4 may represent a novel target to modulate YAP signaling output in cancer treatment or regenerative medicine." (PMID 36522128, 2022). "Indeed, VGLL4 has been reported to be down-regulated in multiple cancer types, and enhancing VGLL4 function in these tumors can suppress tumorigenesis." (PMID 36522128, 2022). "Moreover, while VGLL1–3 have been reported to promote cancer cell growth, VGLL4 overexpression completely ameliorated the massive hepatocellular carcinoma formation induced by perinatal YAP overexpression in transgenic mice." (PMID 36522128, 2022). "On the other hand, VGLL4’s ability to disrupt YAP1–TEADs interaction indicates that peptide mimics of VGLL4 could potentially be useful for suppressing cancers driven by Hippo pathway dysregulation." (PMID 34150758, 2021). "Interestingly, in various human cancer cell lines, Vgll4 was shown to negatively regulate the transcriptional outcome of Hippo signaling by competing with Yap and Taz for TEADs, therefore inhibiting their function." (PMID 31513014, 2019). "The results showed that VGLL4 was significantly lower in cancer tissues than in normal tissues." (PMID 31748508, 2019). "VGLL4 may be involved in the development of cancer through a variety of signaling pathways." (PMID 31748508, 2019).
cancer (continued). "Recently, a VGLL4-mimicking peptide, also known as Super-TDU, showed disruption of YAP-TEAD interaction and may represent a promising new therapeutic strategy against YAP-driven human cancers." (PMID 33477668, 2021). "Furthermore, we detected the expression of the VGLL4 protein in cancer tissues and adjacent normal tissues from 10 cases randomly selected cases of TNBC and found that the VGLL4 expression in cancer tissues from 7 cases of TNBC (7/10) was lower than that in adjacent normal tissues." (PMID 31748508, 2019).
VGLL4 also shares sentences with these, for which no sentence is quoted: bladder cancer (2 papers); meningioma (2); amyotrophic lateral sclerosis (1); attention deficit-hyperactivity disorder (1); autism spectrum disorder (1); bipolar disorder (1); bladder tumor (1); breast invasive ductal carcinoma (1); Clear Cell Renal Cell Carcinoma (1); ductal carcinoma in situ (1); eating disorder (1); Insulin resistance (1); left ventricular hypertrophy (1); major depressive disorder (1); melanoma (1); mental disorder (1); neurodevelopmental disorder (1); ovarian carcinoma (1); rectal cancer (1).